CAV1 (caveolin 1)
Diseases named in the same sentence as CAV1 in open-access papers (continued):
Sharing a sentence is not in itself a finding about the gene and the disease.
tumor (continued). "Here we investigated the role of stromal Cav1 for growth- and resistance-promoting tumor-stroma interactions during PCa progression with a focus on the impact of stromal fibroblasts." (PMID 28112237, 2017). "To address the molecular basis for the opposite roles for Cav-1 in the regulation of tumor cell proliferation, we initially defined its effect on growth-regulating signaling components." (PMID 29141593, 2017). "Remarkably, the tumor-promoting effects of CAV1−/− fibroblasts were reverted by recombinant overexpression of superoxide dismutase 2 (SOD2), thus implying that oxidative stress is critical for facilitating Cav-1 loss-induced carcinogenesis." (PMID 28546853, 2017). "Caveolin-1 induces caveolae formation in the plasma membrane and is often downregulated in many tumour-derived or oncogene-transformed cells." (PMID 29259259, 2017). "TGF-β promotes metabolic alterations in the tumor microenvironment via “metabolic reprogramming” of CAFs through aberrant TGF-β signaling and loss of stromal caveolin-1 (CAV1)." (PMID 28067804, 2017). "Because VEGF-A is the most prominent angiogenic factor secreted by MAMs that stimulates vascular permeability and tumor cell extravasation, we tested the relevance of this ligand in Cav1 KO macrophages." (PMID 29212030, 2017). "Human CAV1 gene is localized to a suspected tumor suppressor locus (7q31.1), which is a fragile genomic region and often deleted in cancers, suggesting that Cav-1 is possibly a tumor suppressor." (PMID 28546853, 2017). "In summary, we demonstrate here for the first time that stromal Cav1 is a critical regulator of the sensitivity of PCa to IR in human PCa PC3 xenograft tumors with impact on tumor growth delay after local irradiation." (PMID 28112237, 2017). "In tumor-bearing mice, MAMs isolated from lung metastases displayed the highest levels of Cav1 expression in comparison to TAMs or other immune cells sorted from either the primary tumor or pulmonary metastasis." (PMID 29212030, 2017). "It has been proven that Src kinase-dependent caveolin-1 (Cav1) phosphorylation increased tumor cell migration in a Galectin-3-dependent manner." (PMID 29254179, 2017). "To confirm the biological effects of Cav‐1 deficiency‐induced premature senescence in vivo, we examined the effects of Cav‐1 knockdown in a xenograft tumor mouse model." (PMID 28514055, 2017). "Recent reports showed that caveolin-1 is a candidate tumor suppressor gene and participates in the pathogenesis of oncogenic cell transformation and tumorigenesis." (PMID 29221140, 2017). "Analyses in samples from HCC patients revealed that tumour tissues presented higher expression levels of CAV1 compared with surrounding non-tumoural areas." (PMID 29022911, 2017). "Cell cycle progression, DNA synthesis, and colony forming ability were markedly decreased by Cav-1 transfection in low-expressing tumor cells but by its depletion in high-expressing cells." (PMID 29141593, 2017). "High metastatic tumoral Cav-1 expression was marginally related with vascular invasion (P = 0.069), and low expression of Cav-1 in the stroma of the primary tumor was significantly related with diffuse type of Lauren classification (P = 0.045)." (PMID 28828003, 2017). "In low- and high-expressing tumor cells, Cav-1 evokes the opposite effects on cell proliferation and colony formation through the reciprocal control on the RAF-ERK negative feedback loop." (PMID 29141593, 2017). "Regarding its tumor promoting function, higher expression of Cav-1 drives into tumorgenesis by inhibiting apoptosis." (PMID 28390134, 2017). "By contrast, tumor suppression and survival were severely compromised in mice that received CAV1−/− DCs." (PMID 29326695, 2017).
tumor (continued). "Meanwhile, Cav-1 also has a feedback regulation effect on oxidative stress status in tumor microenvironment." (PMID 28546853, 2017). "In this study, we more thoroughly investigated the impact of CAV1 on the TGF-β response in HCC cell lines and found out that CAV1 is critical to blunt the tumour-suppressor function of TGF-β in HCC cells." (PMID 29022911, 2017). "Based on these xenograft studies, it’s apparent that cav-1 expression is needed in order to support tumor angiogenesis." (PMID 28187162, 2017). "On the other hand, high CAV1 in the mitochondria suppresses proliferation in H-Ras driven tumour cell model." (PMID 27852311, 2016). "This association remained significant when Gleason score and local tumor stage were combined with Caveolin-1 in a Cox regression model." (PMID 27764093, 2016). "It has been demonstrated that caveolin-1, or Cav-1, produced by the fibroblasts promotes the rigidity of the tumour microenvironment through the activation of GTPasa, thus stimulating tumour progression." (PMID 26913068, 2016). "Our results support that Cav-1 promotes tumor growth under hormone therapy through the upregulation of ACC1-FASN." (PMID 27331874, 2016). "Cav-1 is expressed in smooth muscle cells that dedifferentiate and often loose their Cav-1 expression during tumor progression." (PMID 27764093, 2016). "Cav-1 immunoreactivity in the tumor epithelium was significantly correlated to Cav-1 tumor stroma (r = -0.65, p<0,005, n = 40)." (PMID 27764093, 2016). "In cancer models including prostate, breast and colon, Cav-1 expression is known to be upregulated and correlates with tumor progression and metastasis." (PMID 26919102, 2016). "We therefore examined if altered expression of Cav-1 in the tumor stroma and in the surrounding TINT is related to other functionally important changes in the tumor stroma, and if it can be used to predict outcome also in patients followed without treatment." (PMID 27764093, 2016). "Stronger staining of Cav-1 and NT1-MMP in tumor lung tissues derived from the Cav-1 Y14D group than those derived from LKO or Cav-1 shRNA groups (black arrows indicated)." (PMID 26919102, 2016). "Patients with low tumor Cav-1 had significantly shorter cancer specific survival than patients with high tumor Cav-1 (10-year probability of event-free survival, P-EFS, was 20 ± 9.5% and 77 ± 3.5% in the two groups)." (PMID 27764093, 2016). "The intensity and distribution of Cav-1 staining (both in the tumor and TINT stroma) did vary between patients and to some extent also between different tissue cores in the same individual." (PMID 27764093, 2016). "Taken together, the results from in vivo study demonstrate for the first time that Cav-1 is an important regulator of tumor growth and metastasis." (PMID 26919102, 2016). "These preferences of CAV1 expressing cells contribute to tumor cell attachment and metastasis formation in the lungs of mice." (PMID 27259249, 2016). "Regarding its tumour promoting function, it has been reported that high expression of CAV1 drives tumourigenesis by inhibiting apoptosis, facilitating anchorage-independent growth, drug resistance as well as metastasis." (PMID 27852311, 2016). "A large body of evidence favors the notion that CAV1 function as a tumor suppressor or promotor of metastasis is cell context dependent." (PMID 27259249, 2016). "It has been shown that reduction of CAV1 increased the transcriptional activation of b-catenin, a key transcription factor of Wnt signaling pathway, resulting in enhanced tumor invasion." (PMID 27852071, 2016). "In cancer, CAV1 has been suggested to function as a tumor suppressor in early stages of cancer development and later on as a promoter of metastasis and this ambiguity in function is suggested to depend on the cell type and context." (PMID 27259249, 2016). "The cut-off used in survival analysis was the first quartile (= 2.8) for tumor stromal Cav-1 staining, i.e. high tumor stroma Cav-1 immunoreactivity was ≥2.8." (PMID 27764093, 2016).
tumor (continued). "Exposure of tumor cells to the oxidative stressor H2O2 mimicked this response, causing hyperoxidation of Prx III and loss of Cav1 expression." (PMID 27389535, 2016). "Codeficiency of CAV1 and the tumour suppressor, adenomatous polyposis coli, enhanced colorectal tumourigenesis in mice." (PMID 27852311, 2016). "Our results show that levels of P-gp and other molecules involved in drug resistance such as FASN and Cav-1 are elevated in tumor excised from obese mice treated or untreated with DTIC as compared to mice kept on ND." (PMID 27980732, 2016). "In a cancer context, low CAV1 and high glycolytic phenotypes would suggest a tumour suppressor function, but contradicts its role as a tumour promoter." (PMID 27852311, 2016). "In line with previous studies we also found that Cav-1 in tumor stroma was weakly inversely correlated to tumor size, tumor stage, Gleason score and metastasis at diagnosis, and to PSA-relapse in surgically treated men." (PMID 27764093, 2016). "Caveolin-1 (CAV-1) participates in regulating vesicular transport, signal transduction, tumor progression, and cholesterol homeostasis." (PMID 27124120, 2016). "Our data showed roughly equivalent detection of nanocapsule drug in both tumor types, suggesting that, although caveolin 1 protein levels were higher in PC3-LN4 xenografts, there was sufficient caveolin 1 in 22Rv1 xenografts for similar levels of drug entry." (PMID 27557516, 2016). "Results showed that knockdown of Cav-1 effectively suppressed tumor colonization and nodules formation in mice lungs compared with LKO group." (PMID 26919102, 2016). "Our data reveal that caveolin-1 modulates cell-surface proteome turnover at hypoxia with potential implications for specific targeting of the hypoxic tumour microenvironment." (PMID 27094744, 2016). "In the present study tumor stroma Cav-1 added prognostic information in addition to current clinical prognostic markers such as GS and local tumor stage." (PMID 27764093, 2016). "It is likely that by being co-expressed with FASN, CAV1 ensures availability of the lipids required for maintaining membrane integrity of tumour cells." (PMID 27852311, 2016). "On the other hand, CAV1 acts as a tumour suppressor in some settings in that its low expression favours tumour progression." (PMID 27852311, 2016). "Tumor initiation was markedly decreased in Cav-1 knockdown cells, with only 8 of 30 (27%) injected mice developing tumors, compared to 18 of 30 (60%) injected mice with control cells (p < 0.05, Fisher’s exact test)." (PMID 26065715, 2015). "A semi-quantitative analysis of IHC staining was performed and tumours were classified in 4 categories according to the percentage of Cav1-positive carcinoma cells: 0%; 1-25%; 26-75%; > 75%." (PMID 26474461, 2015). "Analysis of Cav1 expression using a real-time qRT-PCR approach on RNA extracts from fresh-frozen tumours confirmed a strong and significant decrease of Cav1 expression in “R1” patients as compared to “non-R1” tumours." (PMID 26474461, 2015). "Cav-1 is secreted as a biologically active molecule of caveolae that promotes cell survival and angiogenesis within the tumor microenvironment, and is overexpressed in the metastatic and primary sites of several tumors." (PMID 26066055, 2015). "This Registered report describes the proposed replication plan of key experiments from ‘Biomechanical remodeling of the microenvironment by stromal caveolin-1 favors tumor invasion and metastasis’ by Goetz and colleagues, published in Cell in 2011." (PMID 26179155, 2015). "It has been reported that stromal pS6 increased in the fibroblasts embedded within the tumors in Caveolin-1 knock out mice and the authors related that finding with angiogenesis and with breast tumor hormone-independent growth." (PMID 26098779, 2015).
tumor (continued). "Though increased tumor growth in Cav1 knockout mice is expected be rather a long-term effect of Cav1-deficiency, these observations make a careful validation of such treatment strategies with respect to adverse growth promoting effects absolutely necessary." (PMID 25985209, 2015). "Similar work confirmed that mammary pads of Cav-1 null mice generated a lethal tumor microenvironment and constitutively underwent autophagy by increased oxidative stress and inflammatory cytokines, which provides recycled nutrients to feed cancer cells." (PMID 26431273, 2015). "Previously, Cav-1 expression has been correlated with increased tumor diameter, poor histopathologic grade, and poor prognosis in a clinical cohort of 79 Japanese PC patients." (PMID 26065715, 2015). "Prognostic role of Cav1 expression in brain metastasis: Expression of Cav1 in human cancer cell lines and tumor samples has been documented in numerous studies, and it is increasingly clear that its role depends on the tumor type and stage." (PMID 26315660, 2015). "Since CAV1 is linked to disease progression and metastasis in different malignancies, we sought to investigate the role of CAV1 within the tumor microenvironment." (PMID 26566034, 2015). "Silencing Cav1 via lentiviral RNAi miR133a was shown to delay tumor growth in vivo, cell migration and invasion." (PMID 26474461, 2015). "Cav-1 gene is primarily recognized as a tumor-suppressor, although tumor-promoter activities have been described in some contexts." (PMID 25658089, 2015). "Genetic downregulation of Cav-1 via siRNA resulted in reductions in cell proliferation and colony formation using multiple pooled Cav-1 siRNAs, compared with scrambled control siRNA, indicating that Cav-1 has specific roles in tumor cell proliferation." (PMID 26065715, 2015). "Sample of non-tumor site specimens all showed high expression of caveolin-1 with heterogeneous distribution in ductal epithelial." (PMID 26172389, 2015). "Caveolin-1, which is suppressed in many tumor cells and in oncogene-transformed cells, regulates the mechanical phenotype." (PMID 26189182, 2015). "The potential roles for TGF-β1 regulation of Cav-1 in tumor biology and fibrosis require further study." (PMID 25658089, 2015). "Taken together, these results demonstrate a role for CAV1 in the tumor microenvironment of mature T-cell malignancies and point toward potential prognostic implications." (PMID 26566034, 2015). "In order to evaluate the impact of the deregulation of Cav1 expression on the propensity of tumour cells to form distant metastasis, we generated a cell line expressing low level Cav1 and performed functional analysis (shRNAcav1-SCC9)." (PMID 26474461, 2015). "In cancer, Cav1 is involved in cellular transformation, tumor growth, cell death and survival, multidrug resistance, angiogenesis, cell migration and metastasis." (PMID 26315660, 2015). "The phorbol ester 4β-TPA was employed as a generic tumor promotor with the objective of establishing how increasing CAV1 expression correlated with malignacy in these cells." (PMID 26054531, 2015). "These figures are important to replicate as they show that Cav1 expression in fibroblasts contributes to remodeling of the tumor microenvironment in vivo, and that this remodeling correlates with the amount of metastasis." (PMID 26179155, 2015). "β-Catenin transcriptional activity represses p16INK4A transcription, leading to bypass of senescence, and the putative tumour suppressors mir-203 and mir-199a-5p, resulting in regulation of CAV1." (PMID 26307673, 2015). "We have previously reported that ectopic expression of PTRF in PC3 cells results in an increased expression of Cav-1, and yet reduced PCa cell lymphangiogenic and angiogenic potential, tumour growth and metastasis in vitro and in vivo." (PMID 26328273, 2015).
tumor (continued). "We show that CAV1 was expressed at low levels in normal proliferating endometrium, but was readily detectable in endometrial samples of human adenocarcinomas of tumor grades 1-3, as well as in ECC lines." (PMID 26054531, 2015). "Meanwhile, hybridization of Cav-1 knockout mice with tumor prone transgenic mice (MMTV-PyVT) decreased tumor development latency, doubled tumor burden and lung metastatic lesions." (PMID 26431273, 2015). "Goetz and colleagues evaluated metastatic tumor growth where they reported an increase in metastatic foci when tumor cells were coinjected with WT pMEFs compared to tumor cells alone or tumor cells coinjected with Cav1 KO pMEFs." (PMID 26179155, 2015). "Cav-1 has been shown to inhibit a number of oncogenic signalling pathways and function as a tumour/transformation suppressor." (PMID 25756273, 2015). "In tumor tissues with the reverse Warburg effect, Caveolin-1 levels should be restored and the transport of energy-rich metabolites interrupted to cancer cells." (PMID 26437417, 2015). "Caveolin-1 (Cav1) is an essential component of caveolae and regulator of lipid raft formation that plays an important role in tumor progression." (PMID 26179155, 2015). "During cancer transformation and initiation, Cav-1 acted as a tumor suppressor gene in breast, lung, cervical, gastric, glioma and pancreatic malignancies." (PMID 26431273, 2015). "Caveolin-1 (Cav1), a 21-24-kDa protein involved in caveolae formation, is downregulated in many tumor-derived or oncogene-transformed cells." (PMID 26189182, 2015). "In summary, our data demonstrate a pro-tumorigenic role for Cav-1 in PC cell proliferation, tumor initiation, tumor growth, invasion, migration and multimodality therapeutic resistance." (PMID 26065715, 2015). "Our data demonstrate that endothelial Cav1 functions as another critical regulator of vascular function and microvascular sensitivity to ionizing radiation with impact on radiation-induced tumor growth delay." (PMID 25985209, 2015). "In this study, we demonstrate the existence of a complex signalling network involving reciprocal interactions among PTEN, CAV1 and β-catenin; regulating molecular and cellular mechanisms that play a critical role in tumour initiation and progression." (PMID 26307673, 2015). "Bradykinin also induces transcellular transport within blood tumor barrier endothelium with increased expression of caveolin-1 and −2." (PMID 25999807, 2015). "Both tumour suppressive and tumour-promoting roles are reported for Cav-1 in cancer, depending on the cancer type, the tumour stage, and the cellular compartment that is analysed." (PMID 26328273, 2015). "Caveolin-1 is a putative tumor suppressor in other malignancies that binds CD147 and suppresses N-glycosylation and CD147-induced fibroblast MMP activation." (PMID 26209327, 2015). "We and others have previously documented the expression of Caveolins in RMS and more recently shown the important contribute of Cav-1 and Cavin-1 on tumor growth." (PMID 26086601, 2015). "A crisis in oxygen availability or a tumor exhibiting a hypoxic signature leads to HIF-α–dependent up-regulation of CAV1 that enhances the oncogenic potential of tumor cells by increasing the cell’s proliferative, migratory, and invasive capacities." (PMID 25633184, 2015). "The role of CAV1 in drug resistance is controversial relying on the tumor types and chemotherapy drugs." (PMID 26039373, 2015). "Potential mediators of this early event in BBB dysfunction include vascular endothelial growth factor, which induces pinocytic vesicles in blood-retinal barrier and blood tumor barrier endothelium in conjunction with increased expression of caveolin-1 and −2." (PMID 25999807, 2015). "We recently reported that stromally expressed Cav1 promotes biomechanical remodeling of the tumor microenvironment, thus fostering tumor cell local invasion and distant metastasis." (PMID 25550395, 2015).